INS (insulin)
Diseases named in the same sentence as INS in open-access papers (continued):
Sharing a sentence is not in itself a finding about the gene and the disease.
Insulin resistance (continued). "Accordingly, increase in the insulin resistance due to increase in BMI or TG might be compensated by additional insulin secretion without elevation of the blood glucose level." (PMID 26881755, 2016). "The initial insult appears to affect iron-mediated insulin resistance rather than defective insulin production; subsequently, pancreatic ß-cell damage and insulin deficiency develop as a result of direct toxic damage by the non-transferrin bound iron to pancreatic ß-cells." (PMID 27872738, 2016). "Since the primary symptom of T2DM is elevated blood glucose due to either lack of insulin or insulin resistance, the present study focused on the factors which modulate blood glucose levels, including postprandial glucose control and glucose uptake in L6 myoblasts." (PMID 27941667, 2016). "In addition, fasting insulin level and HOMA-IR (Homeostatic model assessment- Insulin Resistance) index, a quantitative analysis to measure insulin resistance, were significantly lower in Ex-4-treated OLETF rat group compared to insulin- and saline-treated OLETF rat group." (PMID 27977690, 2016). "The homeostasis model assessment of insulin resistance (HOMA-IR) of NFR-CETPTg and aP2-CETPTg mice were lower compared with WT mice (4.24 ± 1.19, 2.47 ± 0.54, 6.14 ± 3.14, respectively, p < 0.05), which also suggested that insulin sensitivity of aP2-CETPTg mice were higher." (PMID 26973702, 2016). "Erector spinae IMAT has been shown to be associated with higher homeostasis model assessment of insulin resistance (HOMA-IR) and insulin levels in older adults, and thigh IMAT is also associated with poorer insulin sensitivity in obese individuals with and without type 2 diabetes." (PMID 27916865, 2016). "The level of serum insulin may be increased by insulin-resistance, which means that their cells are not responsive to insulin." (PMID 27827939, 2016). "Although mitogen-activated protein kinase kinase (MEK) is a key signaling molecule and a negative regulator of insulin action, it is still uncertain whether MEK can be a therapeutic target for amelioration of insulin resistance (IR) in type 2 diabetes (T2D) in vivo." (PMID 26839898, 2016). "Another facet of BCAA-induced insulin resistance is related to increased BCAA catabolism in the muscle, which leads to incomplete fatty acid oxidation, gives rise to SCAC that allosterically inhibit citrate synthase, results in mitochondrial stress and impairs insulin action." (PMID 27241713, 2016). "High-fat diet also rapidly decreases adipose tissue ChREBPβ expression and insulin sensitivity in wild-type mice, and does not further exacerbate insulin resistance in adipose tissue Rictor knockout mice, implicating adipose tissue DNL as an early target in diet-induced insulin resistance." (PMID 27098609, 2016). "Activation of PKC could induce insulin resistance through numerous mechanisms; one such mechanism is by increasing oxidative stress and activating the IKK-β/IκB-α/NF-κB pathway further driving inflammation and disrupting insulin signaling." (PMID 27128935, 2016). "However, the insulin-stimulated glucose uptake results indicate that insulin resistance is not present in the studied conditions." (PMID 27023799, 2016). "At least in the fasted state, plasma insulin concentration and insulin resistance were significantly reduced without changes in fasting plasma glucose concentrations after 4 weeks of daily consumption of 100 mg (-)-epicatechin, with tea being the major dietary source of this flavonoid." (PMID 27182277, 2016). "Interestingly, it has been shown that the activity of desaturases, including those originating from the salivary glands, decreases in the absence of insulin or during insulin resistance." (PMID 27471733, 2016).
Insulin resistance (continued). "Studies evaluating the impact of insulin resistance and fasting plasma insulin levels on carotid wall thickness are not conclusive, probably due to differences in the methods used for insulin resistance estimation, differences in population studied and different adjustment for possible confounders." (PMID 26861377, 2016). "Generally, when compared with controls, subjects with insulin resistance had significantly higher levels of systolic and diastolic blood pressure, triglyceride, total cholesterol, fasting plasma glucose (FPG), 2-h PG (OGTT), fasting insulin, HbA1c and lower levels of HDL-C." (PMID 27473122, 2016). "Insulin resistance, chronic inflammation, oxidative damage, and dyslipidemia are generally characterized by the activation of the IRS1/PI3K/AKT pathway, particularly, this being the route activated by insulin or insulin-like growth factor 1 (IGF-1) in insulin resistance." (PMID 26999118, 2016). "Because we could not assess insulin secretion, some metabolically healthy individuals might have isolated insulin resistance without the major common metabolic abnormalities." (PMID 27175686, 2016). "Insulin resistance occurred when tissues were impaired and could not respond to insulin efficiently." (PMID 27257845, 2016). "Furthermore, IPGTT and plasma insulin levels showed that mice fed the 0.2% methionine in HFCD diet for 12 weeks did not develop insulin resistance." (PMID 27723801, 2016). "Indeed, in a mouse model of HFD-induced insulin resistance, we showed that muscle triglycerides accumulation was not prevented by fish oil, yet insulin sensitivity improved." (PMID 27258299, 2016). "We attributed the lack of influence of MetS on DR to the balance between insulin resistance and insulin secretory defects, but markers that can be used to evaluate insulin secretory ability, such as the insulinogenic index or C-peptide levels, were not measured in our study." (PMID 27275953, 2016). "However, when brain glucose utilization is decreased, plasma insulin does not necessarily decrease; indeed, during aging, plasma insulin and glucose are commonly mildly elevated and there is a state of mild-moderate insulin resistance." (PMID 27458340, 2016). "M2 macrophages are responsible for maintaining the adipose tissue in an insulin sensitive state, through the anti-inflammatory action of IL-10 and signal transducer and activator of transcription 3 (STAT3) pathways, whereas M1 secrete pro-inflammatory cytokines contributing to insulin resistance." (PMID 27128935, 2016). "Consequently, muscle ERRγ did not mitigate impaired muscle insulin signaling or insulin resistance in these mice." (PMID 27220353, 2016). "Interestingly, these markers were not correlated with insulin, nor with the insulin resistance indices (HOMA-IR and Matsuda Index 3)." (PMID 26132231, 2015). "Notably, it has been shown that KD-fed mice develop hepatic insulin resistance, while insulin responsiveness in WAT is not affected." (PMID 25973847, 2015). "Although IL10 has been reported to be protective against diet-induced insulin resistance, it has also been reported that IL10 does not improve hepatic or systemic insulin sensitivity in high fat feeding and therefore it does not protect against insulin resistance." (PMID 26229237, 2015). "However, neither protein deprivation nor pregnancy altered the insulin:glucose ratio (which was used here as an indicator of insulin resistance), although the increase in the insulin:glucose ratio observed in pregnant rats approached statistical significance." (PMID 25654754, 2015). "There were significant differences in fasting plasma glucose (FPG), insulin, C-peptide, and the Homeostasis Model Assessment - Insulin Resistance (HOMA-IR) index, but not in body mass index (BMI), waist circumference, hemoglobin (Hb) A1c and HOMA - β-cell function (HOMA-%B)." (PMID 26376678, 2015).
Insulin resistance (continued). "Taken together with the results of the ITT, these insulin levels and HOMA indices suggest that plasma insulin, and to a lesser extent, blood glucose levels, decrease more slowly in CS than in CR rats but that CS rats still did not suffer significant insulin resistance at the time of the study." (PMID 26217667, 2015). "In our work, serum insulin and blood glucose levels were both elevated in the medium and high groups, which suggests that insulin sensitivity was impaired by medium and high, but not low TAC doses, showing a dose dependent TAC effect on insulin sensitivity and induce insulin resistance." (PMID 26599323, 2015). "We found that serum insulin concentrations after glucose load were significantly higher in patients with high TG than in patients with normal TG, suggesting that patients of newly diagnosed T2DM with high serum TG may have developed insulin resistance." (PMID 25924608, 2015). "However, not all obese horses are insulin resistant and, on the contrary, insulin resistance can occur in non-obese animals." (PMID 25938677, 2015). "However, many Alzheimer’s disease patients release sufficient insulin to compensate for insulin resistance and do not progress to type 2 diabetes." (PMID 25755673, 2015). "Thus, it has been described that palmitate through TLR2 may induce insulin resistance in myotubes, inducing activation of NF-κB, JNK and p38 and the impairment of vasodilator actions of insulin." (PMID 26055507, 2015). "Although insulin levels were not measured in the current study, sustained consumption of high fat chow can lead to insulin resistance, and this effect of eating high fat chow on insulin sensitivity has been demonstrated in other studies using similar dietary conditions." (PMID 25805560, 2015). "Interestingly, in mice, five weeks of KD feeding induces hepatic insulin resistance, while it does not impact insulin responsiveness in WAT." (PMID 25973847, 2015). "We did not have measures of insulin sensitivity or secretion and cannot rule out the importance of chronic adaptive immune activation among individuals with prediabetes characterized by insulin resistance." (PMID 26458065, 2015). "Reduction in insulin stimulated phosphorylation of the insulin receptor and IRS-1, and reduced activity of PI3-kinase in T2DM suggest that defective insulin signalling may be, at least in part, responsible for insulin resistance." (PMID 25876175, 2015). "Insulin resistance may result from several mechanisms in PCOS women: decreased insulin secretion and/or hepatic clearance, defected gluconeogenesis in the liver and impaired signaling pathways or receptors of insulin." (PMID 26360602, 2015). "Mean (±SD) HOMA-IR in PAI patients (1.9 ± 1.7) does not support common insulin resistance, however, relatively high standard deviation value indicates that some of these subjects may exhibit impaired insulin sensitivity." (PMID 25129652, 2015). "It is possible that the lack of association observed between eating frequency and insulin resistance may be due to measurement error in the biomarker concentrations used to construct the HOMA-IR variable (i.e., fasting insulin and glucose)." (PMID 26305095, 2015). "Despite the elevated basal levels of insulin and higher hepatic TG levels displayed by CD CBA as compared with CD B6 mice, the SRD regime nonetheless triggered hyperinsulinemia in CBA mice, which in turn provoked a significant increase in hepatic TG levels and insulin resistance." (PMID 26085100, 2015). "Although our findings show improvements for fasting insulin, specific measures of insulin sensitivity were not explored in the present meta-analysis, where only one of the included trials looked at insulin resistance and showed non-significant reductions in HOMA-IR." (PMID 26633472, 2015).
Insulin resistance (continued). "Such processes may be operational especially during the early phase of T2DM, during which amylin and insulin syntheses are markedly increased as a consequence of insulin resistance, leading to non-homeostatic UPR and eventually β-cell apoptosis." (PMID 26136651, 2015). "In light of these data and our finding that TUSC5 regulates insulin-stimulated glucose transport in adipocytes, we hypothesized that TUSC5 expression may be reduced in insulin resistance and that PPARγ agonists may work in part by restoring TUSC5 expression levels." (PMID 26240143, 2015). "Furthermore, we cannot investigate the effects of other covariates of insulin transport into the CSF like obesity or insulin resistance, since these variables were not available in the present set of data." (PMID 25965336, 2015). "Furthermore, fasting serum insulin can be used as a surrogate of insulin resistance in epidemiological studies particularly among non-diabetic subjects." (PMID 26241903, 2015). "In postmenopausal women, the absence of progesterone is likely to enhance insulin production and could promote insulin resistance." (PMID 25866757, 2015). "It has been suggested that IR and subsequent compensatory hyperinsulinemia develops earlier than β-cell dysfunction because insulin secretion in insulin-resistant, non-diabetic persons is increased in proportion to the severity of the insulin resistance even though glucose tolerance remains normal." (PMID 27525252, 2015). "Since all of these parameters showed a trend towards alterations consistent with impaired insulin sensitivity, we cannot exclude that the number of studied animals (n = 5) was too low to unravel significant DEHP effects on additional parameters of insulin resistance and impaired glucose metabolism." (PMID 26630026, 2015). "In addition, in many of these obese type 1 patients increased and even massive doses of insulin fail to overcome the insulin resistance resulting in little or no improvement in glycemic control." (PMID 25785209, 2015). "In our study, insulin levels and insulin resistance were not evaluated." (PMID 26617635, 2015). "Insulin resistance is a condition wherein higher than normal insulin levels are needed to provoke normal metabolic responses or where normal metabolic responses are not achieved with normal insulin concentrations." (PMID 25892856, 2015). "Taken together, therefore, we propose that insulin secretion dysfunction, rather than insulin resistance, may play an important role in the progression of T2DM in Chinese patients." (PMID 25924608, 2015). "Moreover, NAFLD leads to hepatic insulin resistance by stimulating gluconeogenesis, and upregulated SREBP-1c may suppress IRS-2-mediated insulin signaling generating a feedforward machinery to further stimulate or worsen NAFLD." (PMID 26504484, 2015). "Low adiponectin plasma levels are associated with augmented VLDL catabolism and coupled with reduced LPL activity in adipose tissue independently of insulin resistance, suggesting a possible direct action of adiponectin on lipid metabolism, independent of its effects on insulin sensitivity." (PMID 25725623, 2015). "Considering that using exogenous insulin could affect fasting plasma insulin level, we did not involve insulin resistance or C-peptide levels in the analysis." (PMID 26696885, 2015). "Significant controversies remained regarding the metabolic action of resveratrol in human; a meta-analysis of 11 randomized controlled trials revealed that resveratrol significantly reduces glucose, insulin, and insulin resistance in diabetic patients but not in nondiabetics." (PMID 26613076, 2015). "In absence of central, hepatic insulin resistance, high plasma insulin levels suppress both mechanisms; this means that an IFG patient should present with increased HGP, i.e. with a higher k3 value, set therefore in the simulations to 1.6 times the NGT reference value." (PMID 26555895, 2015).
Insulin resistance (continued). "Most studies addressing leptin and insulin report that, after adjustment for BMI, leptin levels in PCOS women do not correlate with the chronic insulin levels, while others report that leptin levels in PCOS women did correlate with measures of insulin resistance." (PMID 26124830, 2015). "This progressive decline in beta cell function amidst a background of insulin resistance, which can be severe in many T2DM patients, particularly with the common concomitant presence of obesity, ultimately results in the need for high doses of insulin in many such patients." (PMID 26060825, 2015). "It is conceivable that dysregulation of expression of miRNA-378 could be a component of insulin resistance in skeletal muscle and might be responsible for the decreased PGC-1α response seen after exercise in insulin resistant skeletal muscle, possibly by a feedback mechanism." (PMID 25984722, 2015). "This might contribute to the fact that the body cells could not use insulin effectively due to insulin resistance (defects in insulin-related signaling)." (PMID 26783411, 2015). "In order to elucidate the mechanism how LXRs participate in the process of gluconeogenesis and why this phenomenon occurs only in the diabetic models with insulin resistance (not in the WT), we further investigated the relationship between the insulin pathway and LXRs." (PMID 25909991, 2015). "Additionally, reduced insulin levels and HOMA-IR in CGI-58-ATko mice on HFD suggest that the reduction in circulating FA levels due to impaired AT-lipolysis counteracts the development of whole body and possibly hepatic insulin resistance." (PMID 25733154, 2015). "In addition, we had no access to information regarding insulin levels or measures for insulin resistance." (PMID 24636522, 2014). "While the fasting glycemia levels were not modified either over time or between genotypes, fasting insulin levels increased significantly in animal of both genotypes but more dramatically in the SHHFcp/cp group indicating the development of an insulin resistance (IR)." (PMID 24831821, 2014). "Previously, it was demonstrated that a short infusion of anti-TNF-α monoclonal antibodyinfliximab induced a rapid and dramatic reduction in serum insulin levels and insulin resistance along with a rapid improvement of insulin sensitivity in nondiabetic AS patients." (PMID 24757680, 2014). "As compared to LZ, OZ exhibited increased hyperglycemia after hemorrhage, which may be due to impaired glucose uptake due to a greater insulin suppression and/or baseline insulin resistance in OZ, but not glucagon secretion." (PMID 25472607, 2014). "Both pancreatic and plasma levels of insulin but not glucagon were markedly elevated but glucose concentrations were relatively normal, indicating the effectiveness of markedly enhanced beta cell activity to overcome severe insulin resistance." (PMID 24967820, 2014). "It has been proposed that the phenotypic expression of the thrifty gene may be hyperinsulinemia or insulin resistance, although this appears to be paradoxical as a decrease in insulin sensitivity suggests a negative impact on fat storage ability." (PMID 25337808, 2014). "The other selective antagonist tested in this study, C108297, also provides modest attenuation in hyperglycemia and peripheral insulin resistance and no changes to insulin response in vivo or β-cell function in this ROD model despite increased ex vivo β-cell response." (PMID 24642683, 2014). "Thus, insulin resistance is not a synchronous, all-or-nothing process but rather builds in select organs or tissues amidst normal insulin response." (PMID 25486190, 2014). "However, high levels of fasting serum insulin in the SHHFcp/cp rats reflecting the development of an insulin resistance, rather than type 2 diabetes were detected as early as 1.5 months of age." (PMID 24831821, 2014).